AHNAK2 (AHNAK nucleoprotein 2)
Diseases named in the same sentence as AHNAK2 in open-access papers (continued):
Sharing a sentence is not in itself a finding about the gene and the disease.
glioma (7 papers, 2021 to 2025). A benign or malignant brain and spinal cord tumor that arises from glial cells (astrocytes, oligodendrocytes, ependymal cells). "In case of young age groups, there are some genes implicated to other cancers whose role in glioma has to be elucidated, yet, like AHNAK2 and SUSD2." (PMID 33639927, 2021). "Conversely, lower expression levels of AHNAK2 were observed in glioblastoma multiforme, glioma (GBMLGG), brain lower grade glioma, breast invasive carcinoma, and prostate adenocarcinoma." (PMID 41465903, 2025). "MYBL2, GNG10, and AHNAK2 exhibited an elevated gene expression in recurrent gliomas, suggesting involvement in cancer progression (e.g., MYBL2 p = 5.5 × 10−6)." (PMID 39684661, 2024). "Additionally, an analysis of the regulatory mechanisms that contribute to cancer development has revealed that subclonal mutations of AHNAK and AHNAK2 in GBM can impact crucial molecules and processes linked to glioma progression." (PMID 38166029, 2024). "By analyzing the regulatory mechanisms underlying the risk subclonal mutations, we found that the subclonal mutations of AHNAK and AHNAK2 in GBM and those of NF1 and PTEN in LGG could influence some important molecules and functions associated with glioma progression." (PMID 35496054, 2022). "The identification of MYBL2, RBM6, VEPH1, AHNAK2, GNG10, and DUSP14 as key genes offers valuable insights into the molecular mechanisms underpinning glioma progression and its interaction with COVID-19." (PMID 39684661, 2024). "Research in the relationship between AHNAK2 and glioma is still lacking." (PMID 38033502, 2023).
papillary thyroid carcinoma (7 papers, 2020 to 2026). "Ahnak2 is a novel prognostic marker and correlates with immune infiltration in papillary thyroid cancer." (PMID 41596666, 2026). "Additionally, AHNAK2 was correlated with immune infiltration in LUAD and papillary thyroid cancer." (PMID 35251577, 2022). "However, a systematic investigation of AHNAK2 in papillary thyroid carcinoma (PTC) has not been conducted." (PMID 32966238, 2020). "The results of the TISIDB analysis suggested that AHNAK2 has positive correlations with 28 tumor-infiltrating lymphocyte (TIL) types and human leukocyte antigens (HLAs) across human cancers, which is particularly significant in THCA (papillary thyroid carcinoma in TCGA)." (PMID 32966238, 2020).
gastric cancer (6 papers, 2020 to 2024). A primary or metastatic malignant neoplasm involving the stomach. "One study found that gastric cancer patients with PIK3CA, LRP1B and AHNAK2 mutations had a better prognosis, and that investigating the molecular mechanisms of the three-gene interaction has potential value in improving the prognosis of gastric cancer." (PMID 38033502, 2023). "DNA methylation status analysis of cancer and normal cells from a patient with Epstein-Barr virus (EBV)-associated gastric cancer (GC) revealed increased AHNAK2 in cancer cells, with a possibility that silencing of AHNAK2 may increase chemosensitivity." (PMID 35158796, 2022). "Another study constructed a clinical prediction model for gastric cancer using AHNAK2 as a factor and validated that the model has some predictive value for recurrence and prognosis." (PMID 38033502, 2023). "A final and significant outcome of our study is the identification of a restricted number of genes which are up-regulated (IRF1, CTSS, PSMB10, CYP26B1, DHRS3 and TINAGL1) and down-regulated (AHNAK2) by ATRA in all the retinoid-sensitive gastric-cancer cell-lines considered." (PMID 37951921, 2023). "In gastric-cancer, AHNAK2 expression is involved in the resistance to chemotherapeutics." (PMID 37951921, 2023). "A study looking at one case of EBV gastric cancer found methylation of AHNAK2, which is hypothesised to be the reason why EBV GC might have a high sensitivity to chemotherapy." (PMID 35158796, 2022). "AHNAK2 functions in cell adhesion and cell junction processes; it has also emerged as a novel prognostic factor for PTC and gastric cancer." (PMID 37795451, 2023). "Finally, AHNAK2 is the only gene, which is down-regulated by ATRA in sensitive gastric-cancer cells." (PMID 37951921, 2023). "In gastric cancer, S100A10 and AHNAK2 are common DEGs that might be involved in Salmonella infection; however, annexin A2 is not, suggesting that the pathway might be actin independent or another protein is recruited to actin assembly sites at cellular membranes." (PMID 39228892, 2024).
lung cancer (6 papers, 2022 to 2026). A malignant neoplasm involving the lung. "A study reported that The Cancer Genome Atlas (TCGA) database revealed a high mutation rate of AHNAK2 in lung cancer, which reached 18.8%." (PMID 38033502, 2023). "And a collection of 12 specimens from patients with brain metastases from lung cancer was sequenced, and the mutation rate of AHNAK2 in lung cancer patients with brain metastases was found to be as high as 26.9%." (PMID 38033502, 2023). "It is of note that AHNAK2 was recently reported to be a positive predictor of immunotherapy in lung cancer." (PMID 36980598, 2023). "Western blot showed decreased SMAD3 phosphorylation in both lung cancer cell lines, with silenced AHNAK2 stimulated by TGF-β1, compared to normal controls." (PMID 35158796, 2022). "Analysis of five Oncomine databases found increased AHNAK2 mRNA expression in lung cancer compared to normal tissue, and IHC slides from the Human Protein Atlas (HPA) database confirmed an increase in protein expression." (PMID 35158796, 2022). "Through the MAPK pathway or the TGF-beta/Smad3 pathway, AHNAK2 promoted lung cancer progression, which involves cell proliferation, migration, invasion, and epithelial–mesenchymal transition." (PMID 36091120, 2022). "AHNAK nucleoprotein 2 (AHNAK2) may play a role in calcium signaling and is upregulated in lung cancer." (PMID 40957660, 2025).
lymph node metastasis (6 papers, 2017 to 2024). "AHNAK2 expression was significantly high in patients with advanced stage, advanced T classification, lymph node metastasis, increased BRAF mutations and decreased RAS mutations." (PMID 32966238, 2020). "In the sub-group of patients with AJCC grade greater than II or lymph node metastasis, a lower OS was significantly associated with higher AHNAK2 expression." (PMID 28423668, 2017). "Patients with higher expression of AHNAK2, lymph node metastasis, or a higher AJCC stage had a lower OS." (PMID 28423668, 2017). "Furthermore, AHNAK2 had significant predictive ability in sub-groups of patients with AJCC grade greater than II or lymph node metastasis." (PMID 28423668, 2017). "We also explored the relationship between AHNAK2 expression and tumor stage and lymph node metastasis in LUAD patients, observing an increase in AHNAK2 expression with advancing tumor stages, followed by a decrease." (PMID 39593730, 2024). "Univariate Cox regression revealed lymph node metastasis (P < 0.001), TNM stage (P = 0.004), and AHNAK2 expression (P = 0.017) were significantly correlated with prognostic." (PMID 32904605, 2020). "The predictive value of increased expression of AHNAK2 remains relevant in patients with AJCC grade above II (n=43, P=0.006) or lymph node metastasis (n=32, P=0.004)." (PMID 28423668, 2017).
melanoma (5 papers, 2020 to 2025). A malignant, usually aggressive tumor composed of atypical, neoplastic melanocytes. "AHNAK2 is expressed in all muscle cells, and its encoded protein interacts with S100B and other proteins to participate in cell structure and calcium signal transduction, and is related to melanoma." (PMID 41479783, 2025). "It is of note that in these three cases AHNAK2, MUC4, MUC16, and MUC17 mutations were found, which were previously reported to be involved in antitumoral immune mechanisms of melanoma." (PMID 36980598, 2023).
pancreatic ductal adenocarcinoma (5 papers, 2017 to 2024). An infiltrating adenocarcinoma that arises from the epithelial cells of the pancreas. "AHNAK2 over-expression has been identified in various cancer cohorts, including pancreatic ductal adenocarcinoma, a largely incurable, aggressive, and silent malignancy." (PMID 35158796, 2022). "This further supports the hypothesis that AHNAK2 likely has an oncogenic role in pancreatic ductal adenocarcinoma." (PMID 35158796, 2022). "A recent study reported that AHNAK2 might be a biomarker for pancreatic ductal adenocarcinoma (PDAC); however, tissue-based experiments have not been conducted." (PMID 28423668, 2017).
bladder tumor (2 papers, 2022). "Immunohistochemistry for AHNAK2 showed the positive staining intensity in bladder tumor samples, stronger than in the normal urothelium tissues." (PMID 35558555, 2022). "In addition, the knockdown of AHNAK2 significantly weakened the invasive capacities of bladder tumor cells." (PMID 35558555, 2022).
cystitis (2 papers, 2022 to 2023). Inflammation of the urinary bladder. "This confirmed the findings, with AHNAK2 IHC staining differentiating between cystitis and CIS with a sensitivity of 97% and a specificity of 69%." (PMID 35158796, 2022). "Out of 3515 identified proteins, AHNAK2 and Keratin 6A (KRT6A) were chosen for IHC validation, due to having the highest ratio of means (over 58 and 29 times more abundant in high-grade cancer compared with cystitis)." (PMID 35158796, 2022). "AHNAK2 was found to be highly expressed in high-grade cancer tissue and CIS, with almost no expression in tissue with cystitis." (PMID 35158796, 2022).
prostate carcinoma (2 papers, 2021 to 2023). A carcinoma that arises from epithelial cells of the prostate gland. "Our scRNA-seq analysis detected greater expression of ANXA3, ANXA2, ANXA2P2, and AHNAK2 in aggressive prostate cancer." (PMID 37476073, 2023). "While the expression of other prostate cancer EMT markers HAS-3, AHNAK2, TGFBR2, ANXA2, and ANXA3 was higher in DU145 compared with DUTXR (Fig. 1CII–IV)." (PMID 37476073, 2023).
systemic lupus erythematosus (2 papers, 2020 to 2025). An autoimmune multi-organ disease typically associated with vasculopathy and autoantibody production. "Diseases associated with AHNAK2 include Charcot–Marie–Tooth (CMT) disease type 4F, and according to GWAS studies, systemic lupus erythematosus, rheumatoid arthritis, and systemic scleroderma." (PMID 41465209, 2025). "Related reports of AHNAK2 in systemic lupus erythematosus (SLE) indicate its potential link with immunity." (PMID 32966238, 2020).
brain malformations (1 paper, 2021). "We also found genes related to disorders of neuronal migration and brain malformations such as polymicrogyria, like AHNAK2 and PI4KA43." (PMID 34702870, 2021).
breast tumors (1 paper, 2025). "CD109, AHNAK2, and MFGE8 in breast BRCA1-mut cancers, and B3GNT7, CTSV, and GSDMC in BRCA2-mut breast tumors." (PMID 40647506, 2025).
cardiomyopathy (1 paper, 2021). A disease of the heart muscle or myocardium proper. "A gene related to cardiomyopathy (ANKRD1) and another related to Duchenne muscular dystrophy (AHNAK nucleoprotein 2, AHNAK2) also showed increased expression in IOPD." (PMID 33922238, 2021).
cervical adenocarcinoma (1 paper, 2022). An adenocarcinoma arising from the cervical epithelium. "Together, these data demonstrated that AHNAK2 is a potential biomarker of cervical adenocarcinoma." (PMID 36017889, 2022).
Charcot-Marie-Tooth disease (1 paper, 2024). An inherited degenerative disorder involving the peripheral nerves. "AHNAK2 is a causative gene in autosomal recessive form of Charcot-Marie-Tooth disease (CMT) which has significant genetic and clinical symptoms overlap with that of ALS." (PMID 39835009, 2024).
esophageal cancer (1 paper, 2023). A primary or metastatic malignant neoplasm involving the esophagus. "Knockdown of AHNAK2 resulted in increased radioresistance in esophageal cancer KYSE-150 cells." (PMID 38033502, 2023). "Whole-exome sequencing analysis of esophageal cancer cells with AHNAK2 knockdown revealed that AHNAK2 may act through NF-κB and TNF signaling pathways to regulate the expression of interleukins, interleukin receptors and chemokines." (PMID 38033502, 2023).
kidney cancer (1 paper, 2020). Primary or metastatic malignant neoplasm involving the kidney. "AHNAK2 high expression is associated with PDAC poor prognosis and is also expressed in bladder and kidney cancer." (PMID 32005189, 2020).
leukemia (1 paper, 2023). A malignant (clonal) hematologic disorder, involving hematopoietic stem cells and characterized by the presence of primitive or atypical myeloid or lymphoid cells in the bone marrow and the blood. "The AHNAK2 protein is supposed to participate in calcium signaling and cytoarchitecture and the BM niche-calcium homeostasis is suggested to be crucial during leukemia initiation." (PMID 37817179, 2023).
pancreatitis (1 paper, 2016). Inflammation of the pancreas. "AHNAK2 and ECT2 also showed elevated levels of expression in the matched PDAC tissue compared to normal or pancreatitis (fold change ~5-8), but the levels of these fold changes relative to normal and pancreatitis tissues were not significantly different." (PMID 26993610, 2016). "These three genes, thus, may reflect different pathophysiological functions from the two genes, AHNAK2 and ECT2 that are increased to a similar degree in PDAC when compared to pancreatitis or healthy pancreas." (PMID 26993610, 2016).
squamous cell carcinoma (1 paper, 2022). A carcinoma arising from squamous epithelial cells. "Together with the results reported in literature, our findings on the different expressions of AHNAK2 in various histological types (including squamous cell carcinoma and adenocarcinoma) suggest that AHNAK2 may be a unique oncogene and a suitable diagnostic marker in adenocarcinoma." (PMID 36017889, 2022).
thyroid tumor (1 paper, 2023). A benign or malignant neoplasm affecting the thyroid gland. "On the other hand, AHNAK2, GPX1, KRT19, and SFN show higher expression levels in thyroid tumors." (PMID 37795451, 2023).
tumor (44 papers, 2015 to 2026). "It was also reported that AHNAK2 mutation remodeled the tumor microenvironment, including elevating the infiltration of M1 macrophages, B cells, and fibroblasts, leading to impaired response to chemotherapy." (PMID 39830210, 2024). "In present studies reported AHNAK2 is among the most frequently mutated genes in several tumor types." (PMID 38033502, 2023). "When we looked at all SNV, we discovered previously undescribed mutations shared between tumor-organoid pairs, such as AHNAK2 and LAMA1 (shared between EDO 74 and 82) and LILBR2 (shared between EDO 92 and 74)." (PMID 32884042, 2020). "Patients with NSCLC harboring AHNAK2 mutations exhibit higher tumor mutation burden (TMB), indicating enhanced tumor immunogenicity, and these mutations are associated with an activated immune microenvironment, marked by increased immune cell infiltration and activation." (PMID 40124684, 2025). "In multiple types of cancers, abnormal expression of AHNAK and AHNAK2 is associated with prognosis, and they play a key regulatory role in tumor progression by activating signaling pathways such as ERK, MAPK, Wnt, and MEK, as well as promoting epithelial-mesenchymal transition." (PMID 38033502, 2023). "The results showed that AHNAK2 deficiency may lead to the loss of contact between extracellular matrix and adjacent cells, thus inducing anoikis which is closely related to cell migration and tumor metastasis." (PMID 36017889, 2022). "To investigate the expression levels of AHNAK2 in normal tissues and tumors, we utilized the R software package to download and analyze AHNAK2 expression data from TCGA across various tumor types and their corresponding normal tissues." (PMID 41465903, 2025). "Immunohistochemical staining of sections from patients with PMMC revealed statistically significant increases in expression of SIRPB1, AHNAK2, and XKR6 in tumor-associated regions compared with adjacent tissue." (PMID 41479783, 2025). "In PDAC, elevated AHNAK2 levels promote tumor progression by preventing c-MET degradation, thereby sustaining HGF/c-MET pathway activation." (PMID 40308776, 2025). "Our study provides compelling evidence of a robust association between AHNAK2, the prognosis of PAAD, and the tumor immune microenvironment." (PMID 41465903, 2025). "Knockdown of AHNAK2 has been shown to impede tumor progression through inhibition of the NF-κB/MMP-9 signaling pathway." (PMID 40308776, 2025). "AHNAK2 and SLC2A1 were primarily expressed in epithelial cells, while CD27 and LTB were predominantly associated with T cells, potentially influencing tumor immunity." (PMID 39593730, 2024). "The expression of chemoresistance genes has been detected, including KLF4 (doxorubicin and ifosfamide), ULK1, LUM, GPNMB, and CAVIN1 (doxorubicin), and AHNAK2 (gemcitabine) in tumor cells and ETS1 (gemcitabine) in TME." (PMID 39685635, 2024). "Del-AHNAK2-mut was further found to be strongly associated with tumor mutational burden (TMB), neoantigen load (NAL) levels and tumor-infiltrating immune cell (TIIC) to better predict patient PFS and OS." (PMID 38033502, 2023). "Knockdown of AHNAK2 impairs hypoxia-induced epithelial mesenchymal transition and stem cell properties of tumor cells." (PMID 38033502, 2023). "Of these genes, only AHNAK2 has been previously reported to be directly related to tumor ME and has thus been chosen in this study for further investigation." (PMID 37817179, 2023). "We also observed somatic mutations in other RCC‐associated genes, such as PBRM1 and AHNAK2, most of which were conserved between RCC organoids and the corresponding tumour tissues." (PMID 35802820, 2022). "Consistent with the results obtained with bioinformatics, it was revealed that CA12 and AHNAK2 mRNA levels were significantly upregulated in tumor tissues compared to adjacent tissues, whereas MMAA and DMBT1 mRNA levels were downregulated analogously." (PMID 35847888, 2022).